TNFSF15 (TNF superfamily member 15)
Diseases named in the same sentence as TNFSF15 in open-access papers (continued):
Sharing a sentence is not in itself a finding about the gene and the disease.
ovarian carcinoma (6 papers, 2016 to 2023). A malignant neoplasm originating from the surface ovarian epithelium. "Another study identified tumor necrosis factor superfamily-15 (TNFSF15), an endogenous suppressor of neovascularization, plays a critical role in the physiologically normal ovary but is lost in ovarian cancer." (PMID 28929459, 2018). "We reported previously that TNFSF15 downregulation in ovarian cancer is facilitated by VEGF secreted by cancer cells." (PMID 28097093, 2017). "We showed previously that VEGF effectively down-regulate TNFSF15 expression in ovarian cancer, indicating that TNFSF15 as a negative regulator of blood vessel growth is targeted by VEGF for down-modulation in order to initiate angiogenesis." (PMID 27589684, 2016). "In ovarian cancer, elevated VEGF could effectively inhibit TNFSF15 production by ECs, and downregulation of TNFSF15 is a pre-requisite for tumor neovascularization." (PMID 27120595, 2016).
atherosclerosis (5 papers, 2013 to 2025). A disease characterized by the build-up of fatty material and calcium deposition in the arterial wall resulting in partial or complete occlusion of the arterial lumen. "Additionally, 4 genes (Tnfsf15, Tlr3, Nlrp3, and Lepr), which have known roles in cholesterol efflux and atherosclerosis, were present in the network." (PMID 27239478, 2016).
ileitis (5 papers, 2011 to 2021). "Mice with forced constitutive expression of TNFSF15 (TL1A-tg) in either the lymphoid or myeloid cell compartments demonstrated a stable phenotype of mild ileitis." (PMID 30972074, 2019).
prostate carcinoma (5 papers, 2013 to 2024). A carcinoma that arises from epithelial cells of the prostate gland. "Here, TNFSF15 expression was inversely associated with prostate cancer risk." (PMID 33197890, 2020). "In this study, we constructed a model using a Cox proportional hazards model based on the expression of eight immune-related genes that were associated with prognosis in prostate cancer: EDNRB, ANGPTL2, TNFSF15, TNFRSF10D, EDN2, BMP2, NLRP14, and PLK1." (PMID 33197890, 2020). "This is consistent with the role of TNFSF15 as a downstream effector of AMPK that inhibits prostate cancer growth." (PMID 33197890, 2020). "TNFSF15 inhibits the growth of prostate cancer cells and bovine aortic endothelial cells in vitro, supporting that LITAF may function as a tumor suppressor." (PMID 30871256, 2019). "Besides that, LITAF inhibits cell proliferation by specially binding to the same consensus motif, CTCCC (−515 to −511), and activating transcription of TNFSF15 in prostate cancer." (PMID 27764808, 2016). "More interestingly, LITAF and TNF superfamily member 15 (TNFSF15) is up-regulated by 5′ adenosine monophosphate (AMP)-activated protein kinase (AMPK) in LNCaP and C4-2 prostate cancer cells." (PMID 23414097, 2013).
colon cancer (4 papers, 2018 to 2022). "Increased TNFSF15 expression levels can inhibit growth of colon cancers and are associated with early stage of chronic lymphocytic leukemia." (PMID 35887121, 2022). "For colon cancer, the high expression of TNFSF15 gene isoforms was related to tumor progression and encoded two protein molecules (TL1A and VEGI-192), which can be considered as independent prognostic factors." (PMID 34859010, 2021).
gastric cancer (4 papers, 2014 to 2022). A primary or metastatic malignant neoplasm involving the stomach. "Genotype frequencies of TNFSF15 polymorphisms among gastric cancer patients and controls and their association with the risk of gastric carcinoma." (PMID 25251497, 2014). "In this study we have evaluated the influence of TNFSF15 and H. pylori infection on gastric cancer susceptibility and found there was a joint effect of −358C allele and H. pylori infection in raising the risk of gastric cancer." (PMID 25251497, 2014). "In view of the importance of TNFSF15 in tumor progression and metastasis, we hypothesized that the TNFSF15 SNPs in promoter region may influence protein expression and function, which confers susceptibility to gastric cancer." (PMID 25251497, 2014). "In this case, it would be expected that TNFSF15 genetic variants might contribute to the development of gastric cancer by inhibiting the TNFSF15 expression." (PMID 25251497, 2014). "Consequently, the risk of gastric adenocarcinoma associated with the TNFSF15 genotype was further examined by stratifying gastric cancer patients by H. pylori infection status." (PMID 25251497, 2014). "Risk estimates for extended TNFSF15 haplotypes in gastric cancer patients and controls." (PMID 25251497, 2014). "Risk of gastric carcinoma associated with TNFSF15 genotypes by H. pylori infection status." (PMID 25251497, 2014). "In addition, some TNFSF15 SNPs have been considered gastric cancer risk factors." (PMID 34859010, 2021). "Therefore, in this study we sought to identify the functional polymorphisms in the promoter of TNFSF15 gene and conduct a case-control study to investigate the frequency of these SNPs and the possible association with the risk for developing gastric cancer in the Chinese population." (PMID 25251497, 2014). "Several previous studies from our laboratory also provided the evidence that the effect of genetic variants in TNFSF15 and XAB2 on the susceptibility to gastric cancer could be modified by age." (PMID 35111412, 2022).
viral infection (4 papers, 2017 to 2024). "Activation of TNFRSF25 by its ligand, TNFSF15, is important for T‐cell proliferation during viral infection control as it enhances interferon‐g (IFN‐g) synthesis." (PMID 36039012, 2023).
COVID-19 (3 papers, 2021 to 2023). A disease caused by infection with severe acute respiratory syndrome coronavirus 2. "Of the DEGs that overlapped between healthy and COVID-19 PBMCs, 17 were upregulated, among which IL1R2, whereas the genes encoding for the cytokine tumor necrosis factor superfamily member 15 (TNFSF15) and ACOD1 were downregulated by dexamethasone." (PMID 37614228, 2023). "TNFSF15 is a third immune response protein in the XCR1 RR subnetwork that shows elevated expression in patients with severe COVID-19." (PMID 34616619, 2021). "A summary data-based Mendelian randomization (SMR) analysis and a transcriptome-wide association study (TWAS) were performed for the severe COVID-19 dataset, and seven novel genes for severe COVID-19 were identified, including CCR5, CCR5AS, IL10RB, TAC4, RMI1, and TNFSF15." (PMID 36483456, 2022). "We speculate that IL17RD, CD74, and TNFSF15 may serve as disease biomarkers in COVID-19." (PMID 36483456, 2022). "Thus, we speculate that IL-17RD, CD74, and TNFSF15 might serve as disease biomarkers for COVID-19." (PMID 36483456, 2022).
diabetes (3 papers, 2016 to 2024). "Treatment of diabetic rats with TNFSF15 prevented the decrease in claudin-5, occludin, and ZO-1 protein levels caused by diabetes (95.8% ± 10.6%, 85.4% ± 9.2% and 94.1% ± 11.7% of the control, respectively), indicating that TNFSF15 mediates the expression of TJPs." (PMID 27120595, 2016). "First, TNFSF15 expression increased under high glucose conditions, likely as an endogenous protective response, consistent with other research showing upregulation of TNFSF15 in diabetes." (PMID 38331883, 2024). "In summary, our findings reveal TNFSF15 is a natural brake on GSDME-triggered retinal cell pyroptosis induced by diabetes." (PMID 38331883, 2024). "TNFSF15 was dramatically decreased one month later after diabetes induction (p < 0.001), and then increased three months later and thereafter." (PMID 27120595, 2016). "Diabetes induced an obvious decrease in the TNFSF15 protein level in the retina of rats to 14.8% ± 3.4% and 72.6% ± 9.9% in the DM1 and DM3 groups compared with that of the control group, respectively (F = 57.738, p < 0.001)." (PMID 27120595, 2016). "One month after diabetes induction, the weight gain in the DM group, DM+vehicle group, and DM+TNFSF15 group was dramatically less when compared with controls, whereas the blood glucose levels were dramatically higher." (PMID 27120595, 2016). "Diabetes decreased TJPs levels in the retina, and these changes were inhibited by TNFSF15 treatment." (PMID 27120595, 2016). "Moreover, TNFSF15 decreased activation of VEGF both in mRNA and protein levels caused by diabetes." (PMID 27120595, 2016). "TNFSF15 could be successfully overexpressed in the retina by injecting of LV-TNFSF15-GFP intravitreally (1 μL, 1 × 1010 TU/mL) 2 weeks after diabetes induction." (PMID 27120595, 2016).
diabetic retinopathy (3 papers, 2016 to 2024). "This study explored the role of GSDME-mediated pyroptosis and its regulation by TNFSF15 in diabetic retinopathy." (PMID 38331883, 2024). "This study aimed to explore the potential role of TNFSF15 in diabetic retinopathy." (PMID 27120595, 2016). "Collectively, our results demonstrate TNFSF15 inhibits diabetic retinopathy progression by blocking GSDME-dependent pyroptosis of retinal cells, suggesting the TNFSF15-GSDME interaction as a promising therapeutic target for diabetic retinopathy." (PMID 38331883, 2024).
diverticulitis (3 papers, 2019 to 2024). An infection that develops in the diverticula of the intestinal tract. "Two smaller studies found an associated SNP in the TNFSF15 gene in the subset of patients requiring surgery for diverticulitis; TNFSF15 encodes a cytokine in the TNF family and has been associated with severe IBD56,99,100." (PMID 38831715, 2024). "This study strengthens therefore the role for a genetic predisposition to diverticulitis that involves the TNFSF15 immunoregulatory gene, triggering the occurrence of inflammation as a consequence." (PMID 31001067, 2019). "Four replicated loci, ARHGAP15, COLQ, FAM155A and TNFSF15, are highlighted to have a stronger association with diverticulitis and may have a role in inflammation." (PMID 38831715, 2024). "Interestingly, besides IBD, Tnfsf15 genetic variants have also been associated with other GI diseases, such as diverticulitis and Irritable Bowel Syndrome (IBS)." (PMID 30972074, 2019). "This study demonstrates clearly that distinct but overlapping TNFSF15 haplotypes can be found in diverticulitis patients versus healthy controls when compared with the known CD haplotype suggesting similar but distinct genetic predispositions." (PMID 31001067, 2019). "Taken together, various SNPs of the Tnfsf15 gene have been associated with not only IBD, but also diverticulitis and IBS, and seem to be promising predictors for intestinal disease susceptibility and/or progression." (PMID 30972074, 2019).
glioma (3 papers, 2021 to 2024). A benign or malignant brain and spinal cord tumor that arises from glial cells (astrocytes, oligodendrocytes, ependymal cells). "The research demonstrated that NF‐κB and AP‐1 are positively correlated with TNFSF15 expression in glioma." (PMID 33300633, 2021). "The expression of HAVCR2, PVR, TNFRSF25, and TNFSF15 showed a positive correlation with the expression of numerous MRM-related genes like GTPBP3, METTL2A, METTL6, METTL8, NSUN4, and TRMT61A in glioma cells." (PMID 38824202, 2024). "The anti‐angiogenesis gene TNFSF15 showed a 30‐fold increase in glioma development, with an increasing expression of NDRG1, and demonstrated that anti‐angiogenesis was positively correlated with TNFSF15." (PMID 33300633, 2021). "In glioma cells, it was observed that the expression of genes related to MRM, like GTPBP3, METTL2A, METTL6, METTL8, NSUN4, and TRMT61A, showed positive correlation with the expression of HAVCR2, PVR, TNFRSF25 and TNFSF15 as revealed by scRNA-seq analysis." (PMID 38824202, 2024).
melanoma (3 papers, 2016 to 2024). A malignant, usually aggressive tumor composed of atypical, neoplastic melanocytes. "TNFSF15 is not expressed in either B or T cells, so it is probably expressed in melanoma cells." (PMID 36675674, 2022).
Salmonella Infections (3 papers, 2017 to 2022). Infections with bacteria of the genus SALMONELLA. "We corroborated our findings by mining publicly-available data from a recent eQTL study in MDM with and without Salmonella infection, confirming that the IBD risk allele is associated with lower MDM TNFSF15 expression." (PMID 30199539, 2018).
systemic lupus erythematosus (3 papers, 2021 to 2024). An autoimmune multi-organ disease typically associated with vasculopathy and autoantibody production. "We found a disease-associated increase in Ly6Clow patrolling monocytes that expressed high levels of TLR7 and had upregulated expression of lupus-associated IL-10, CD115, CD31, and TNFSF15 in NZBWF1 mice." (PMID 34868046, 2021).
gastric adenocarcinoma (2 papers, 2014 to 2019). "In our previous study, we found that TNFSF15–638A > G polymorphism was associated with the development of gastric adenocarcinoma." (PMID 30736740, 2019). "In the present study, we identified two genetic variants (−358T>C and −638A>G) in the promoter of TNFSF15 gene and examined their influence on TNFSF15 transcriptional activity and the susceptibility to gastric adenocarcinoma in Chinese populations." (PMID 25251497, 2014). "Subjects carrying the TNFSF15 −358CC genotype were at an elevated risk for developing gastric adenocarcinoma, compared with those with the −358TT genotype (OR 1.42, 95% CI, 1.10 to 2.03)." (PMID 25251497, 2014). "In our previous study, we identified two SNPs (−638A > G and -358 T > C) in the TNFSF15 promoter by direct sequencing, and found that -358 T > C variant changed the transcriptional activity of TNFSF15 and was significantly associated with the susceptibility to gastric adenocarcinoma." (PMID 30736740, 2019). "Collectively these findings indicate that functional genetic variants in TNFSF15 may play a role in increasing susceptibility to gastric adenocarcinoma." (PMID 25251497, 2014). "In the H. pylori infected group, subjects with TNFSF15 −358CC genotype were at higher risks for gastric adenocarcinoma compared with those carrying −358TT genotype (OR: 2.01, 95%CI: 1.65 to 4.25), indicating that H. pylori infection further influenced gastric adenocarcinoma susceptibility." (PMID 25251497, 2014). "The subjects with TNFSF15 −358CC genotype were at elevated risks for developing gastric adenocarcinoma compared with those with −358TT genotype in the H. pylori infected group, but not in the H. pylori negative group." (PMID 25251497, 2014). "The purpose of this study was to identify functional genetic variants in the promoter of tumor necrosis factor superfamily member 15 (TNFSF15) and evaluate their effects on the risk of developing gastric adenocarcinoma." (PMID 25251497, 2014).
lung carcinoma (2 papers, 2019 to 2023). "In this study, we explored the association of TNFSF15 variants with the susceptibility to lung cancer and found that -638A > G and -358 T > C variants elevated the risk of SCLC, but not of NSCLC." (PMID 30736740, 2019). "We used unconditional logistic regression to assess the association of TNFSF15 SNPs with the risk of lung cancer." (PMID 30736740, 2019). "This study aimed to investigate the correlations between TNFSF15 polymorphisms and genetic susceptibility to lung cancer." (PMID 30736740, 2019). "Tumor necrosis family superfamily member 15 (TNFSF15) promotes lymphatic metastasis by upregulating vascular endothelial growth factor-C in a lung cancer mouse model." (PMID 38022627, 2023).
scleritis (2 papers, 2020 to 2022). Inflammation of the sclera. "Our results showed that a TNFSF15 CCC haplotype was associated with an increased susceptibility to develop scleritis." (PMID 33287909, 2020). "In this study, haplotype analysis showed that a TNFAIP3 TGT haplotype, a TNFSF4 GT haplotype, and a TNFSF15 CCC haplotype were significantly associated with scleritis." (PMID 33287909, 2020). "This study reveals that a TGT haplotype in TNFAIP3 may be a protective factor for the development of scleritis and that a GT haplotype in TNFSF4 and a CCC haplotype in TNFSF15 may be risk factors for scleritis in Chinese Han." (PMID 33287909, 2020). "In conclusion, we identified the association of various TNF gene related haplotypes with scleritis in Chinese Han, including TGT in TNFAIP3, GT in TNFSF4, and CCC in TNFSF15." (PMID 33287909, 2020). "In addition, a study on the genotypes of TNF-α-related genes in Chinese Han patients with scleritis found that specific haplotypes in TNFAIP3 (TNF-α-induced protein 3), TNFSF4 (TNF-αreceptor superfamily member 4), and TNFSF15 might be the risk or protective factors of scleritis in Chinese Han." (PMID 36431163, 2022). "The TNFSF15 CCC haplotype frequency was discovered to be significantly increased in scleritis cases without as well as with systemic diseases, as compared with healthy volunteers (Pc = 0.039, OR = 1.579, 95% CI = 1.096–2.274; Pc = 0.027, OR = 2.496, 95% CI = 1.229–5.067, respectively)." (PMID 33287909, 2020). "The TNFSF15 CCC haplotype frequency was significantly increased in the anterior scleritis group (Pc = 0.003, OR = 1.860, 95% CI = 1.267–2.730), but this was not seen in the other scleritis groups." (PMID 33287909, 2020).
Spondyloarthritis (2 papers, 2009 to 2015). "Identification of a link between the DR3/TL1A pathway and the spondyloarthritides was first demonstrated when single-nucleotide polymorphisms (SNPs) located in the direct vicinity of the TNFSF15 gene were shown to be strongly associated with predisposition to spondyloarthropathy." (PMID 26065008, 2015).
Stroke (2 papers, 2014 to 2023). Sudden impairment of blood flow to a part of the brain due to occlusion or rupture of an artery to the brain. "We also compared TNFSF15 gene expression in subgroups according to frequency of painful crises, history of ACS, and stroke." (PMID 25330517, 2014). "TNFSF15 belongs to the tumor necrosis factor (TNF) ligand family induced by TNF and IL-1α, which plays an important role under disease conditions, such as cancer and stroke, by maintaining vascular and lymphatic vessel homeostasis." (PMID 36936375, 2023).
acute chest syndrome (1 paper, 2014). A vaso-occlusive crisis of the pulmonary vasculature occurring in patients with sickle cell disease. "TNFSF15 gene expression was compared in subgroups considering the frequency of painful crises and acute chest syndrome (ACS)." (PMID 25330517, 2014).
ANCA-associated vasculitis (1 paper, 2018). "Importantly, in both cohorts of healthy volunteers and the cohorts of IBD and ANCA-associated vasculitis patients, the IBD protective allele (A, the minor allele in the European population) was consistently associated with increased expression of TNFSF15." (PMID 30199539, 2018).
bacterial pneumonia (1 paper, 2014). Acute infection of the lung parenchyma caused by bacteria (e.g., Streptococcus pneumoniae, Haemophilus influenzae, Chlamydia pneumoniae, Mycoplasma pneumoniae, and Legionella pneumophila). "Enhanced Fas, Fap, Il24, and Tnfsf15 expression is observed following LIF depletion in animals with bacterial pneumonia, which could contribute to the increased apoptosis observed here." (PMID 25277705, 2014).
cervical carcinoma (1 paper, 2022). A carcinoma arising from either the exocervical squamous epithelium or the endocervical glandular epithelium. "For immunostimulator, SLC30A1 expression positively correlated with IL6R (Spearman: ρ = 0.204, P = 0.000345), TNFSF15 (Spearman: ρ = 0.355, P = 2.19e-10), NT5E (Spearman: ρ = 0.299, P = 1.16e-07), and PVR (Spearman: ρ = 0.236, P = 3.29e-05) in cervical carcinoma." (PMID 35154468, 2022).
clear cell renal cell carcinoma (1 paper, 2024). "-TNFSF15 was identified as a gene linked with tumor suppression-Expression was higher in younger ccRCC clear cell renal carcinoma tissues than in older patients." (PMID 38590525, 2024). "Our team previously revealed that TNFSF15 gene expression was downregulated in clear cell renal cell carcinoma of geriatric with negative association between the TNFSF15 gene expression and age." (PMID 38590525, 2024).